BCL2 (BCL2 apoptosis regulator)
Diseases named in the same sentence as BCL2 in open-access papers (continued):
Sharing a sentence is not in itself a finding about the gene and the disease.
ovarian carcinoma (continued). "Survivin, c-Myc and Bcl-2 play active roles in cell proliferation and maintenance of ovarian cancers and are known as the common target genes of Wnt, Notch and STAT3 signaling." (PMID 25896424, 2015). "In contrast, paclitaxel-resistant ovarian cancer cells displayed increased Bcl-2 expression, but failed to induce phosphorylation of Bcl-XL or Bcl-2 after BPR0L075 exposure." (PMID 23762410, 2013). "The other anti-apoptotic Bcl-2 familly members, such as Mcl-1, Bcl-W or Bcl-G have not been extensively investigated in ovarian cancer." (PMID 24281100, 2010). "In SKOV-3 ovarian cancer cells HNTMB treatment led to chromatin fragmentation and activation of the extrinsic and intrinsic pathways of apoptosis with specific down-regulation of Bcl-2." (PMID 20184758, 2010). "In the present study, 57% (16/28) of the ovarian cancer specimens showed positive Bcl-2 staining in more than 5% of the tumor cells regardless of cancer stage." (PMID 19852858, 2009). "Similarly, in ovarian carcinoma cells, paclitaxel-induced apoptosis is inhibited by ET-1 (via ETAR), triggering antiapoptotic signalling through bcl-2-dependent and phosphatidylinositol 3-kinase-mediated AKT pathways." (PMID 15226779, 2004). "Despite these findings, significance of BCL-2 or BAX expression in ovarian cancer response to cisplatin-based chemotherapy has not been confirmed by clinical studies." (PMID 12644821, 2003). "We conclude that BAX expression may represent a prognostic indicator for patients with ovarian cancer and that the combined evaluation of BAX and BCL-2 may provide additional prognostic significance." (PMID 11720475, 2001). "In sublines possessing acquired resistance to various platinum-based drugs or across a panel of human ovarian carcinoma xenografts, there was no consistent pattern of BCL-2 expression." (PMID 10646901, 2000). "Additionally, in CRC cells and ovarian cancer cells, ISL induced apoptosis through upregulating anti‐apoptotic regulator Bax (also known as Bcl‐2‐like protein 4) and downregulating pro‐apoptotic regulator Bcl‐2." (PMID 40013655, 2025). "Therefore, we demonstrated that CryZ could act as Bcl-2 and Bcl-xl AUBP in A2780 ovarian cancer cells." (PMID 39021835, 2024). "In ovarian cancer cells, ISA can reduce the phosphorylation of Akt, which may also contribute to the ROS overproduction and GSH depletion, as well as the downregulation of Bcl-2." (PMID 39376605, 2024). "We found that our anti-OSMR monoclonal antibodies reduced the ovarian cancer cell growth and progression by inhibiting STAT3 activation and subsequent oncogenic signaling operated through STAT3, inhibiting the levels of survival regulators such as BCl2, PCNA, and inducing cell death." (PMID 38839865, 2024). "Interestingly, BITC inhibited Bcl-2 expression and up-regulated the expression of caspase-3, caspase-8, c-PARP, and Bax, seemingly via activation of JNK1/2/p38 and inhibition of ERK1/2 and Akt signaling in ovarian cancer cells." (PMID 37190316, 2023). "We demonstrated that platinum resistance, which is mediated by cisplatin-induced ERCC-1, MRP-2, and XIAP in SKOV3 ovarian cancer cells (with a moderate level of HOXB9 expression), could be overcome by cisplatin treatment alone through the inhibition of Bcl-2 and activation of Bax." (PMID 36674764, 2023). "Conversely, induction of DRP1 through inhibiting anti-apoptotic proteins BCL-2 or activating Sirt3 (histone deacetylase) by ABT737 (an inhibitor of antiapoptotic BCL-2/BCL-X) promotes fission, leading to apoptosis and mitophagy in ovarian cancer cells resistant to cisplatin." (PMID 35326612, 2022). "DHM also impairs the motility and invasiveness of ovarian cancer SKOV3 and A2780 cells and stimulates the c-Jun N-terminal kinase (JNK)/ERK-caspase-3 pathway, leading to apoptosis by upregulating the cleaved caspase-3 and Bax/Bcl-2 ratio in ovarian cancer cells." (PMID 35884547, 2022).
ovarian carcinoma (continued). "Similarly, another BCL‐2 inhibitor, ABT‐263 (Navitoclax), was reported to eliminate senescent cells and enhance the efficacy of olaparib, a poly(ADP‐ribose) polymerase (PARP) inhibitor, in both breast and ovarian cancer cell lines." (PMID 34137158, 2021). "And in this study, SLT was proved to increase the apoptosis rate of ovarian cancer cells through mitochondrial apoptosis pathway with the increased protein levels of cleaved caspase-3, cleaved PARP, Bax, and cytochrome C (in the cytoplasm), while the Bcl-2 level was decreased." (PMID 33869638, 2021). "Thus, both ovarian cancer cell lines PA1 and A2780 were treated with 10, 20, and 40 nM of ST09 drug for 48 h and the expression of pro-survival factor BCL-2, pro-apoptotic proteins Bax and Bak, cytochrome C, apoptosome complex protease Apaf-1, and cleaved caspase 9 were evaluated." (PMID 34837026, 2021). "In another example, miR-142-5p targeted several antiapoptotic genes, including baculoviral IAP repeat-containing 3 (BIRC3), B-cell lymphoma-2 (BCL2), BCL2-like 2 (BCL2L2), and myeloid cell leukemia sequence 1 (MCL1), and could improve cisplatin-mediated anticancer function in ovarian cancer." (PMID 31861383, 2019). "Our siRNA-loaded PLGA nanoparticles for co-delivering MDR1 and BCL2 siRNA provide an efficient combination therapy strategy to overcome the chemoresistance of paclitaxel and cisplatin on the paclitaxel-resistant SKOV3-TR and cisplatin-resistant A2780-CP20 ovarian cancer respectively." (PMID 29760419, 2018). "Consequently, we consider that the Bcl-2 selective compound ABT-199 is unlikely to be efficacious in most ovarian cancers." (PMID 27080533, 2016). "BCL-XL, rather than BCL-2, might be responsible for the enhanced sensitivity of ovarian cancer cell lines to ABT-737." (PMID 24523919, 2014). "Therefore, RUNX1 cannot directly regulate the activity of the BCL2 promoter, and the investigators found that RUNX1 can regulate BCL2 through the miR-17–92 cluster in ovarian cancer, which may be part of the mechanism via which RUNX1 regulates BCL2 to further regulate apoptosis." (PMID 37760803, 2023). "In conclusion, the platinum resistance of SKOV3 ovarian cancer cells may be different in terms of its refractoriness to cisplatin treatment according to the level of HOXB9 overexpression and the subsequently induced expression of ERCC-1, MRP-2, and XIAP, as well as Bcl-2/Bax expression." (PMID 36674764, 2023). "In addition, the competitive inhibitor Navitoclax (ABT-263) shows promise in inhibiting Bcl-XL and Bcl-2 by mimicking the BH3 domain of Bad, and multiple studies have illustrated its ability to decrease overall cell survival and reduce chemoresistance in ovarian cancer." (PMID 33182737, 2020). "Moreover, an inhibitor to prevent Bcl-XL/Bcl-2 from binding to Bax could provide a solution to the lack of cell death in taxane-resistant ovarian cancer." (PMID 33182737, 2020). "In addition, the ectopic expression of ALKBH5 inhibited the autophagy of epithelial ovarian cancer cells in vitro and in vivo, partly through activating EGFR-PIK3CA-AKT-mTOR signaling pathway, promoting the stability of BCL-2 mRNA, as well as enhancing the interaction between Bcl-2 and Beclin1." (PMID 32742194, 2020). "Furthermore, Bcl-2 levels and Bad phosphorylation were examined to determine whether the PI3K-Akt-Bad signaling pathway played a role in regulating cell apoptosis and whether this mechanism was targeted by MAP in ovarian cancer cells." (PMID 23554793, 2013). "Thus, to improve the chance to cure ovarian carcinomas, one should carefully consider whether to employ autophagy inhibitors or autophagy-enhancer drugs in the chemotherapy cocktail depending on the ratio of BECLIN 1 and BCL-2 expression and the actual level of autophagy in the cancer cells." (PMID 25136588, 2014).
ovarian carcinoma (continued). "Previous studies showed that KLF4 was downregulated in ovarian cancers compared to controls and that KLF4 did not affect cell proliferation but increased the Bcl-2/Bax ratio and inhibited apoptosis." (PMID 25137052, 2014). "BCL-2 and BAX, but not MEK1 expressions have predictive value in ovarian cancer patients treated with platinum-based chemotherapy." (PMID 12644821, 2003). "Further experiments indicated navitoclax but not venetoclax could also sensitize OVCAR8 cells to paclitaxel-induced apoptosis, in agreement with the results that most ovarian cancer cells have abundant BCLXL, but not BCL2." (PMID 34385422, 2021). "Interestingly, this group did not see an induction of the pro-survival proteins BIRC2, BIRC3, nor Bcl-2 when COL11A1 was overexpressed in A2780 and ES2 ovarian cancer cell lines, nor a reduction of these proteins when COL11A1 expression was knocked down in A2780CP70 ovarian cancer cell line." (PMID 33668097, 2021).
hepatocellular carcinoma (359 papers, 1996 to 2026). A malignant tumor that arises from hepatocytes. "Separate studies examining osteosarcoma, thyroid cancer and hepatocellular carcinoma cells found that lidocaine-associated apoptosis was accompanied not only by alteration of the Bax/Bcl-2 ratio but also activation of caspases." (PMID 34408981, 2021). "Protopine treatment caused decrease of Bcl-2 and Bcl-xl in a dose-dependent manner in liver carcinoma cells." (PMID 34315493, 2021). "Two PPARγ activators PGJ2 and pioglitazone were reported to induce apoptosis by decreasing Bcl-2 in chronic hepatitis B-associated hepatocellular carcinoma cells." (PMID 30018246, 2018). "These authors suggested that the Bcl-2 protein is a diagnostic marker to distinguish ChC from hepatocellular carcinoma." (PMID 22654601, 2012). "In this study, Bcl-2 expression was enhanced by HBV pre-S2Δ large surface protein and the consequence of Bcl-2 expression was associated with resistance to 5-fluorouracil in hepatoma cells." (PMID 22216150, 2011). "The relevant results showed that increasing in the expression of BNIP3 following the treatment of hepatoma cells with concanavalin A inhibited the expression of Bcl‐2/Bcl‐2‐associated X protein ratio, resulting in mitochondrial dysfunction and the activation of caspase‐dependent apoptosis." (PMID 35243817, 2022). "To further clarify the regulatory mechanism of IVIG-caused apoptosis in hepatocellular carcinoma cells, we evaluated the expression of two vital members from the Bcl-2 family, Bcl-2 and Bax, and the executioner caspase, cleaved caspase-3, at the protein level by Western blotting." (PMID 35874633, 2022). "It was reported that HJT could effectively cause hepatoma cell cycle arrest by upregulating the inactive form of Cdc2 and Cdc25, and downregulating the levels of Bcl-2 and Bcl-xL." (PMID 28702078, 2017). "TTP subsequently promotes apoptosis of hepatocellular carcinoma (HCC) by promoting Bcl-2 mRNA instability associated with caspase-3 enhancement." (PMID 34026612, 2021). "For example, in one study, a hybrid chalcone, chalcone 1C, decreased BCL-2 protein levels in hepatocellular carcinoma cells." (PMID 41141929, 2025). "Previous studies have shown that VILIP3 promotes BCL2 expression in hepatocellular carcinoma cells, which is consistent with our findings." (PMID 40495165, 2025). "The apoptotic protein signal (Bax, Bcl‐2, and cytochrome c) of human hepatoma HepG2 cells was determined by Western blot analysis." (PMID 38628219, 2024). "Matrine-induced Beclin1 upregulation leads to its separation from Bcl-2/Bcl-xL and subsequent autophagy induction, which greatly inhibits the development of hepatocellular carcinoma xenografts." (PMID 39588099, 2024). "After DMF treatment, the Bcl-2/Bax ratio was decreased, indicating that mitochondrial apoptosis occurred in human hepatoma cells." (PMID 39444606, 2024). "Luteolin also promotes apoptosis in SMMC-7721 hepatocellular carcinoma cells by upregulating caspase-8 and downregulating BCL2 protein and mRNA levels." (PMID 40066127, 2024). "ABT-199 (Venetoclax), the first selective Bcl-2 inhibitor, is ineffective against hepatocellular carcinoma cells when used alone." (PMID 38324023, 2024). "The synergistic antitumor effect of luteolin and 5-fluorouracil is related to the increased Bax/Bcl-2 ratio in human hepatocellular carcinoma cells." (PMID 39234106, 2024). "In the present study, we evaluated the expression of Bax and Bcl-2 genes in hepatocellular carcinoma to investigate the regulatory effect of FEGCG and MPI on the Bcl-2 family." (PMID 37277118, 2023).
hepatocellular carcinoma (continued). "Meanwhile, knockdown of CENPH retarded the growth of Hep3B, hepatic carcinoma cell, subcutaneous xenograft, and decreased the expression of Ki-67 and BCL-2." (PMID 37328854, 2023). "For example, the Nur77/ΔDBD gene was reported to downregulate stanniocalcin 2 (STC2) overexpression in hepatocellular carcinoma, which increased the expression of P-gp and Bcl-2." (PMID 37497002, 2023). "Experiments confirmed that SOX11 is a target for miRNA-182, and a decrease in miRNA-182 inhibits the growth of hepatocellular carcinoma cells and downregulates BCL2 expression." (PMID 37894763, 2023). "BMC Cancer 14: 938, 2014; and Gai X, Tu K, Li C, Roberts LR and Zheng X: Histone acetyltransferase PCAF accelerates apoptosis by repressing a GLI1/BCL2/BAX axis in hepatocellular carcinoma." (PMID 37449518, 2023). "Studies have also demonstrated that miR-204 down-regulates the expression of Bcl-2, Sirt1, and Fn-1 to inhibit the proliferation and promote the apoptosis of hepatoma cells and tumor endothelial cells." (PMID 37488484, 2023). "And then, sinapine restrains the proliferation of hepatocellular carcinoma H22 cells by inhibiting the anti-apoptotic factor Bcl-2 and promoting the expression of the pro-apoptotic factor Bax." (PMID 37124205, 2023). "For example, C. wenyujin can increase apoptosis in hepatoma cells by inducing increased expression of apoptotic genes Bid and Bax, and decreased expression of anti-apoptotic gene Bcl2." (PMID 37746000, 2023). "DHM can downregulate Notch1 expression and decrease the Bcl-2/Bax ratio in hepatoma cell lines QGY7701 and HepG2 in a time- and dose-dependent manner, inhibiting the proliferation of hepatoma cells." (PMID 35884547, 2022). "In another study, oleuropein has been shown to effectively inhibit the cell viability and proliferation of hepatocellular carcinoma (HepG2) cells by inducing apoptosis through ROS production, increasing Bax, and decreasing Bcl-2." (PMID 36500466, 2022). "As recently reported, ADA inhibited the growth of ovarian cancer ES-2 cells by targeting glutamicoxaloacetic transaminase 1 (GOT1) and induced apoptosis by regulating the Bax/Bcl-2 ratio in hepatoma cells." (PMID 35273495, 2022). "The point of CHOP crosstalk has been found to induce the nuclear translocation of Bcl-2 to release beclin-1 and induce autophagic apoptosis in hepatocellular carcinoma cells." (PMID 35815056, 2022). "The combination of SMAC mimetics and BCL-2 inhibitors have shown synergistic effect in hepatocellular carcinomas." (PMID 36341439, 2022). "BCL-2 can prevent hepatocellular carcinoma cells from apoptosis and promote tumor formation mainly by blocking the Fas/FasL apoptosis pathway and forming a complex with BAX." (PMID 36313628, 2022). "Encapsulating siRNA for BCL-2 in bubbles has been shown to reduce resistance to paclitaxel (PTX) in hepatocellular carcinomas." (PMID 35745854, 2022). "The vitality and Bcl-2 protein expression level of HuH-7 hepatoma cells decreased significantly (P < 0.05), while the apoptosis rate, Caspase-3, and Bax protein expression increased significantly (P < 0.05) in the circFOXO3 mimic group." (PMID 35909586, 2022).